CD4 (CD4 molecule)
Diseases named in the same sentence as CD4 in open-access papers (continued):
Sharing a sentence is not in itself a finding about the gene and the disease.
infection (continued). "The percentages of splenic NFATc1+ CD4 T cells were remarkably increased with prolonged infection and picked on day 16 (about 60%)." (PMID 36091043, 2022). "Mainly including Th1, Th2, Th17, and induced regulatory (iTreg) cells, activated CD4+ T lymphocytes can further activate the macrophages, recruit macrophages to the infection position, and generate cytokines." (PMID 35265084, 2022). "It has been reported that the CD4+ T lymphocytes play key roles in the control of primary infections with Eimeria spp., and CD8+ T lymphocytes participate in the expression of resistance to reinfection." (PMID 36112763, 2022). "Dendritic cells (DCs) capture parasites at the site of infection and migrate to draining lymphoid organs, where they stimulate the differentiation of naïve CD4+T cells to differentiate into the Th1 subset in a manner dependent on IL-12 production." (PMID 35585983, 2022). "T lymphocytes play an essential role in the immune response against infections, such as those caused by viruses and bacteria; both CD4+ and CD8+ T cells help in removing pathogens during infection." (PMID 35513847, 2022). "Due to abortive infection, caspase-1 is activated by CD4+ T cells through interferon-inducible protein 16 (IFI16)." (PMID 36411423, 2022). "Collectively, these results suggested that Leronlimab reduced infection of target CCR5+CD4+ T cells." (PMID 35358290, 2022). "Infection and establishment of viral latency in the naïve CD4 T cell subset is, perhaps, the most important and unique aspect of our in vitro cell model." (PMID 35895672, 2022). "Blocking LFA-1 and VLA-4 on resting CD4+ T cells inhibited infection by 65.4%–96.9%, indicating that engagement of these integrins facilitates EC-mediated enhancement of productive HIV infection in resting CD4+ T cells." (PMID 34465136, 2022). "Third, a number of recent reports have uncovered a potential role for non-Th1 cells in Chlamydia immunity, or in tissue repair after infection, including Type-II immune cells, Th17 cells, and CD4 T cells secreting IL-13." (PMID 35196366, 2022). "In tissues, modest increases of caspase 3 expression in CD4 T cells were also observed by day 10 following SIVmac251 infection in colon (P = 0.04) and spleen (P = 0.03) with less than 4% tissue-resident CD4 T cells undergoing apoptosis." (PMID 36000842, 2022). "Participants 1 and 2 had high CD4+ T cell levels at the infection stage, and their NDDTs change very slowly." (PMID 35205215, 2022). "The observed enhancement of infection resulting from the interaction between ECs and resting memory CD4+ T cells has clear relevance for HIV acquisition and pathogenesis." (PMID 34465136, 2022). "One of the key aspects of HIV infection is a fast and widespread destruction of CD4+ T-lymphocytes, which becomes more exacerbated in the latest stages of infection." (PMID 36569851, 2022). "CD4 T cell subsets, as with response to infection, are also deleteriously affected following vaccination." (PMID 36119079, 2022). "To evaluate the direct impact of SIVmac251 infection on CD4 T cell death, we quantified the percentage of CD4 T cells containing SIV transcripts." (PMID 36000842, 2022). "The infection frequency per 106 CD4 T cells of the genetically-intact HIV proviruses were calculated for all of these participants, as well as the genetic diversity of these genetically-intact HIV proviruses." (PMID 35916523, 2022). "With the addition of an anti-IL-10 blocking antibody, CD4 T cell control of HCMV Merlin GFP infection increased almost to the level observed with the HCMV Merlin dUL11 GFP infections." (PMID 36445084, 2022). "Type I interferon signaling regulates primary CD4+ T cells, which are necessary for the generation of protective immune responses following vaccination or infection, and thereby determines host survival." (PMID 35225986, 2022). "The number of CD4 T cells was increased at 28 days post infection, while the number of CD8 T cells was similar." (PMID 36118033, 2022).
infection (continued). "After 1 week of infection, M. s_Rv1515c infection caused significant (p < 0.05) decrease in CD3+ T cells and 2-fold decrease in CD4+ T cells." (PMID 35813825, 2022). "People living with HIV-1 who were enrolled into the study were on stable ART, and had an HIV-1 viral load of less than 1000 copies per mL and median CD4 counts of 738 cells per μL (ie, their infection appeared well controlled)." (PMID 35489376, 2022). "In total, 100% of mock-depleted mice, 80% of CD8 T cell-depleted mice, and 40% of CD4 T cell-depleted mice succumbed to infection by 26 dpi." (PMID 36289695, 2022). "This region also contains the amino acid sequence used to make a tetramer to identify Cda2-specific CD4 T cells following infection of C57BL/6 mice." (PMID 35089095, 2022). "There was a steady decline in SARS-CoV-2 memory CD8+ T cells and CD4+ T cells within 8 months after infection." (PMID 34975340, 2022). "Initial parasite survival and proliferation correlated with a Th2 reorientation of the CD4+ T lymphocytes, leading to immunotolerance or to an anergic response to infection at later stages." (PMID 35862712, 2022). "The fungal microbiomes of the HIV and HCV mono-infection groups were significantly different from those of the HC group, and some opportunistic fungi were clearly enriched in low-CD4 + T-cell patients and in high-ALT-level patients." (PMID 36016433, 2022). "Human Immunodeficiency Virus (HIV) attacks the body’s immune system, specifically the CD4+ T cells, which help the immune system fight off infections." (PMID 36417469, 2022). "In the setting of RSV, epitope-specific CD4+ T cells were present in low proportions in the airways prior to infection." (PMID 36211412, 2022). "After recognizing an antigen, CD4 T cells develop into memory CD4 T cells ready to defend against future infections with the pathogen." (PMID 35074048, 2022). "Locally activated CD4+ and CD8+ T cells (with a predominance of CD4+ in early infection) produce IFN-γ." (PMID 35408911, 2022). "HIV-1 and HTLV-1 initially infect mDCs as an intermediate and eventually spread infection to target CD4+ T cells via mechanisms including the formation of virological synapses, viral biofilms, and conduits." (PMID 36146843, 2022). "At two and four weeks post-infection, we assessed CD4+ and CD8+ T cell accumulation in the popliteal lymph nodes and ankle joints of WT and PD-1-/- mice." (PMID 36265003, 2022). "The lung is a crucial site in priming protective immunity against N. brasiliensis where lung-resident CD4+ T cells elicit IL-4Rα dependent protection against secondary infection." (PMID 35264261, 2022). "First, the experiments were performed in CD4+ T-cell lines to more closely represent the main cell type targeted for infection by HIV-1." (PMID 35770989, 2022). "While CD8+ T cells contribute to control of bacterial growth via IFN-γ and TNF-α early in the infection, CD4+ T cells have been shown to be more important in the later stages of infection, especially in cases of reinfection." (PMID 35498397, 2022). "The decline in CD4 T cells was almost always driven by natural processes, although the contribution of new infections increased during periods of VL resurgence (Eq 3)." (PMID 35969641, 2022). "To further describe CD4+ T cell states as they adapt during the course of an acute, self-resolving infection that generates protective memory T cells, we investigated subtype composition and subtype-specific transcriptional changes over time." (PMID 35829695, 2022). "The most established example of this process is the infection of the human immunodeficiency virus (HIV), which is mediated by the binding of HIV gp120 protein with DC-SIGN (CD209), to facilitate the infection of CD4+ T-cells." (PMID 35401532, 2022). "In summary, there is insufficient evidence to show that IFN-γ producing CD4 T cells significantly contribute to the control of infection within the FRT during C. muridarum infection." (PMID 35196366, 2022).
infection (continued). "We found up‐regulation of Notch ligands (NLs) and Notch receptors (NRs) on phagocytes and IFNγ+ CD4+ T cells upon infection in lungs and lymph nodes." (PMID 35603470, 2022). "Consistent with their poor homing, the OVA specific CD4+ T cells also gave rise to significantly lower numbers of monoclonal OT-II effector CD4+ T cells (i.e., CD44hiCD62lo) by day 4 post infection." (PMID 36895258, 2022). "Prior to an infection or vaccination, naïve CD4 and CD8 T cells circulate through the lymphatics awaiting activation from an APC, typically a DC." (PMID 36119079, 2022). "Rapamycin also decreased expression of the HIV/SIV entry coreceptor CCR5 on CD4+ TM cells, potentially increasing their resistance to infection." (PMID 35316218, 2022). "The presence of resident CD4+ T-cells was investigated for the role in activation and progression of inflammation in response to infection with SARS-CoV-2." (PMID 35250984, 2022). "To test this, we adoptively transferred M. tuberculosis Ag85B-specific TCR transgenic (P25TCR-Tg) naive CD4 T cells (labeled with CellTrace Violet) into mice 24h prior to aerosol infection." (PMID 35695454, 2022). "The reduction in CD4 cell counts early in infection was substantially higher in HET than MSM, consistent with the more stringent selection at transmission resulting in more virulent T/F strains in HET than MSM." (PMID 35271687, 2022). "Strikingly, our observations are similar to previous results showing that cell-to-cell transfer of HIV-1 between CD4+ T cells across the virological synapse is less sensitive to anti-CD4 Q4120 antibody than in cell-free infection." (PMID 35622876, 2022). "Whereas the ratio of shCtrl (Amt+) to shCtrl (GFP+) transduced CD4+ T cells remained unchanged 7 days after infection, we found a strong, ~sixfold reduction in the ratio of shCacnb1 (Amt+) to shCtrl (GFP+)-transduced T cells." (PMID 35440113, 2022). "HDAC6 impairs HIV-1-mediated stabilization of a cortex of stable and acetylated MTs in their α-tubulin subunits, which is required for efficient viral entry and infection, and is directly dependent on the first viral Env/CD4 interaction and signaling." (PMID 35682862, 2022). "In general, recent studies suggest that in patients with HIV infection coinfected with HCV or HBV, CD4 recovery rates are lower than in patients with HIV mono-infection." (PMID 36298842, 2022). "Analysis of SARS‐CoV‐2‐reactive CD4 T cells with two upregulated activation markers showed the strongest response at the earliest time‐point, less than 3 months after initial infection which then decreased in magnitude over the next 9 months." (PMID 35396852, 2022). "Remarkably, studies have shown that CD4+ T cells generated upon infection were mostly specific against the M, N, and S proteins of this virus, with comparable numbers, proliferation capacities, and proportions of these cells in several responding patients." (PMID 35632475, 2022). "During P. aeruginosa infections, only CD4-PP treatment at the time of infection reduced the survival." (PMID 35821354, 2022). "Poor resistance of the C57BL76 line was further associated with higher frequencies of IFN-γ competent Th2/1, Th1 and CD4- cells in siLP along the course of infection." (PMID 35690651, 2022). "Since CD8+ T cells are cytotoxic towards HIV‐1, the CD4/CD8 ratio is an important parameter to consider, indicative of the balance between frequency of infectable cells (CD4+) and cells combating infection (CD8+)." (PMID 36302121, 2022). "CD4 cell count/percentage is an important immunological marker that indicates stage of infection and informs antiretroviral therapy." (PMID 36369146, 2022). "Rv1515c upregulates Treg cells during initial phase of infection which suppress T cell generation, whereas during the later phase of infection Treg cells are downregulated which allows the CD4+ T cells to proliferate." (PMID 35813825, 2022).
infection (continued). "At week 4 post infection, activated CD4+CD69+ T cell numbers increased in both groups and the numbers were now equivalent at this timepoint." (PMID 35173157, 2022). "Data from SARS-CoV-2 animal models support the role of T-cell immunity as a correlate of protection from infection and virus-specific CD4+ and CD8+ T-cell responses are considered key players in the resolution and long-term protection from infection." (PMID 35619701, 2022). "The interactions of lymphocyte LFA-1 with ICAM-1 expressed by these DCs, elevated upon infection, maturation and entry into MedLNs, were thought to be critical for functional immune synapses between both CD4+ and CD8+ T cells and antigen presenting DCs." (PMID 36895258, 2022). "CD44 is also a marker of T cell activation, and similarly, significantly increased IFNγ+ and IL-17+ cells were present among CD4+CD44+ T cells from Mtb-HT1 infected mice at week 2 post infection." (PMID 35173157, 2022). "Abortive infection followed by pyroptotic cell death is the fate of the majority of HLAC CD4 T cells." (PMID 35784348, 2022). "CD39+ cells are more activated than CD39- cells, thereby inducing transient expression of CD4 on Vδ2 γδ T cells in vivo and promoting infection." (PMID 35529864, 2022). "Since metabolic pathways were widely regulated in Vhl cKO CD4 T cells during M. tuberculosis infection, we measured the mitochondrial bioenergetic profiles of lung T cells during infection with M. tuberculosis." (PMID 36064840, 2022). "(2020) used murine models percutaneously infected with S. japonicum cercariae to investigate the B-cells profile and its role in CD4+ T-cells regulation, as well as the regulatory role of PD-L1 during infection." (PMID 36148227, 2022). "iNKT and γδT cells, unconventional T cells with innate responsiveness, in the early phase of Mtb infection, and CD4+ T cells after the third week of infection were the major sources of GM-CSF." (PMID 35967869, 2022). "Of interest, the release of pro-inflammatory cytokines by MDM was stimulated by Serinc5 in synergy with the CCR5-antagonist Maraviroc (that prevents infection by blocking virions bound to CD4 on the plasma membrane)." (PMID 35328442, 2022). "The loss of CD4+ Th1 leads to a progressive CD8+ T cell decline and dysfunction with important implications for controlling the infection." (PMID 35887351, 2022). "We first sought to determine cross-reactivity of SARS-CoV-2-specific CD4+ and CD8+ T cells induced following infection with the wt (D614G, wave 1) and Beta variant (wave 2), between each other." (PMID 35880744, 2022). "Excised cervical lymph nodes of Mtb-HIV coinfected individuals had increased Mtb load and fewer CD4+ T cells compared to Mtb mono-infection." (PMID 36405707, 2022). "This barrier to infection can be overcome by exposing resting CD4+ T cells to endothelial cells (ECs)." (PMID 34465136, 2022). "Two weeks after H. polygyrus infection, skin CD4+ T cell numbers began to increase and by 4 weeks after infection T cell numbers were 2–3 times higher than in the skin of uninfected mice." (PMID 34931000, 2022). "We also found that vaccine-induced T-cell immunity following a single dose was dominated by CD4+ responses in previously infected individuals, in contrast to infection-naive participants who mounted more balanced CD4+ and CD8+ anti-spike responses." (PMID 34778853, 2022). "CD4 T lymphocytes can recruit neutrophils to the site of infection by secreting cytokines to help fight invading pathogens." (PMID 36324819, 2022). "In particular, 8 weeks after infection, the average frequency of PD-1 expressing cells peaked at 64.5% in CD4+ T cells, which was a 5.6-fold increase from the uninfected controls." (PMID 35666747, 2022). "In particular, the infection rate of CD8+ TEM was 4.5 times higher than CD4+ Tfh cells and 36.5 times higher than naive CD8+ cells at 16 h.p.i., and all other T subsets are less than 5% at 16 h.p.i.." (PMID 35317717, 2022).
infection (continued). "Id3-GFPlo or Id3-GFPhi SMARTA memory CD4+ T cells (28-32 d following primary infection) were transferred into a new cohort of B6 hosts, which were then infected 1 d later with LCMV." (PMID 35858332, 2022). "Vaccination to prevent infection with pathogens requires robust production of antibodies by B cells, aided by CD4+ T cell help, to neutralize pathogens upon initial infection and reinfection." (PMID 35289317, 2022). "Resting memory CD4+ T cells are the primary infection targets in vivo, and constitute a key cellular reservoir for HIV latency." (PMID 34465136, 2022). "Both vaccination and infection induced spike-specific CD4+ T cell responses, whereas a CD8 response was less consistently detected." (PMID 35102311, 2022). "It has been shown that the presence of both CD8+ and CD4+ T cells producing IFN-γ correlated with a low total symptom score after infection, and viral clearance and reduced shedding in the absence of specific antibodies." (PMID 36146606, 2022). "Following infection or vaccination, dendritic cells (DCs) and B cells act cooperatively to induce and reinforce the differentiation of CD4+ T follicular helper (Tfh) cells." (PMID 35631044, 2022). "In the MLN, the percentage of IL-10+ CD8+ T cells, CD4+ T cells and ILCs increased upon infection, while both IL-10+ B cells and myeloid cells remained unchanged between naïve and infected samples." (PMID 35428872, 2022). "In infection naïve individuals, S-specific CD4+ T cell responses were primed with the first dose of vaccine and further boosted with the second dose." (PMID 35911696, 2022). "We compared BA.1-associated CD4+ and CD8+ T-cell responses among those receiving 0–2 doses (n = 13) vs. 3–4 doses (n = 51) of vaccine prior to infection with BA." (PMID 35927279, 2022). "Nevertheless, the magnitude of CD4+ T-cell response was greater in convalescent with positive serology in comparison with those with past infection who had negativized serology before vaccination (p = 0.013)." (PMID 35529539, 2022). "Our data strongly suggest that CTL responses are correlated with the protection against PRRSV-1 transplacental infection, being executed by CD4 T cells or CD4/CD8α DN cells." (PMID 36798517, 2022). "Only the second wave natural infection group and the Covishield group showed more than 50% response (50% individuals with SI above 2) in terms of CD4-IFNγ and CD4-IFNγ+CD40L respectively." (PMID 37304053, 2022). "In contrast with ThPOK- CD4CTLs that accumulate in the gut, CD4+GzB+ T cells in the T. cruzi-infected spleen express ThPOK at the peak of infection." (PMID 35670567, 2022). "To further avoid potential bias caused by various factors, we conducted a sensitivity analysis in the multivariate model of HIV patients by stratifying the baseline CD4+ cell count and infection period, respectively." (PMID 34895083, 2022). "Unstimulated blood CD4 T cells are highly resistant to abortive infection and pyroptosis unless first cultured with lymphoid tissue cells under conditions where cell-to-cell interactions occur." (PMID 35784348, 2022). "We then compared the global mRNA expression in sorted lung CD4 T cells from Vhl cKO and WT mice 8 weeks after infection with M. tuberculosis." (PMID 36064840, 2022). "Data on immune memory to SARS-CoV-2 are currently limited: in a study on cellular immunity >6 months post-infection, memory CD4+ and CD8+ cells were positive in approximately 90% and 70% of individuals, respectively." (PMID 35891194, 2022). "For HIV, VS require interactions between Env and CD4 to enhance the efficiency of infection and cell-cell spread in vitro." (PMID 35714165, 2022). "Both CD4 and CD8 T-cell activation are necessary for the control of infection and are associated with milder diseases." (PMID 36560586, 2022). "Among these studies, algorithm performance was found to be impacted by patients’ ART status (4/19), HIV viral load (3/19), CD4 count or advanced infection (3/19), and HIV subtype (2/19)." (PMID 35275085, 2022).